NOS1 (nitric oxide synthase 1)
Description:
Produces nitric oxide (NO) which is a messenger molecule with diverse functions throughout the body. In the brain and peripheral nervous system, NO displays many properties of a neurotransmitter. Probably has nitrosylase activity and mediates cysteine S-nitrosylation of cytoplasmic target proteins such SRR.
Synonyms: N-NOS; nNOS; bNOS; IHPS1; NC-NOS; NOS
Tractability: Small molecule: a drug acting on it is in phase 2 or 3 trials; a structure with a bound ligand is known; a high-quality ligand is known; it belongs to a druggable protein family. Antibody: its Gene Ontology location is reachable by antibodies, with high confidence; UniProt places it where antibodies can reach, with medium confidence; the Human Protein Atlas places it where antibodies can reach. PROTAC: UniProt records ubiquitination sites on it; its protein half-life has been measured; a small molecule that binds it is known.
Target class: Enzyme; Oxidoreductase
Gene: Protein-coding gene on chromosome 12 (117,208,142 to 117,452,170, reverse strand). Ensembl gene ENSG00000089250.
Subcellular location: Cell membrane, sarcolemma; Cell projection, dendritic spine
Subcellular location (Human Protein Atlas): Plasma membrane; Nucleoplasm
Pathways (Reactome):
Hemostasis: Nitric oxide stimulates guanylate cyclase
Immune System: ROS and RNS production in phagocytes
Muscle contraction: Ion homeostasis
Gene Ontology:
Molecular function: nitric-oxide synthase activity; peptidyl-cysteine S-nitrosylase activity; protein binding; arginine binding; cadmium ion binding; calcium channel regulator activity; calcium-dependent protein binding; flavin adenine dinucleotide binding; FMN binding; heme binding; NADP binding; scaffold protein binding; sodium channel regulator activity; tetrahydrobiopterin binding; transmembrane transporter binding; calmodulin binding; oxidoreductase activity
Biological process: multicellular organismal response to stress; positive regulation of neuron apoptotic process; response to heat; response to hypoxia; vasodilation; cell redox homeostasis; cellular response to growth factor stimulus; L-arginine catabolic process; myoblast fusion; negative regulation of blood pressure; negative regulation of calcium ion transport; negative regulation of calcium ion transport into cytosol; negative regulation of potassium ion transport; negative regulation of serotonin uptake; nitric oxide biosynthetic process; positive regulation of adenylate cyclase-activating G protein-coupled receptor signaling pathway; positive regulation of DNA-templated transcription; positive regulation of membrane repolarization during ventricular cardiac muscle cell action potential; positive regulation of sodium ion transmembrane transport; positive regulation of the force of heart contraction; positive regulation of transcription by RNA polymerase II; regulation of calcium ion transmembrane transport via high voltage-gated calcium channel; regulation of cardiac muscle contraction; regulation of cardiac muscle contraction by calcium ion signaling; regulation of sodium ion transport; and 13 more
Cellular component: plasma membrane; sarcolemma; sarcoplasmic reticulum; cell periphery; cytoplasm; cytoskeleton; cytosol; membrane raft; mitochondrion; nucleus; perinuclear region of cytoplasm; photoreceptor inner segment; postsynaptic density; protein-containing complex; synapse; calyx of Held; caveola; dendritic spine; endomembrane system; sarcoplasmic reticulum membrane; T-tubule; Z disc
Genetic constraint (gnomAD): Loss-of-function variants: 49 observed, 155.63 expected, observed/expected ratio (o/e) 0.31, 90% interval 0.25 to 0.4. The upper end of that interval is the gene's LOEUF score, 0.4, which puts it in group 1 of 6, group 1 being the genes least tolerant of losing a copy. Missense variants: 1,340 observed, 1,905.7 expected, observed/expected ratio (o/e) 0.7, 90% interval 0.67 to 0.74. Synonymous variants: 711 observed, 765.3 expected, observed/expected ratio (o/e) 0.93, 90% interval 0.87 to 0.99.
Homologues: Orthologues: chimpanzee NOS1 (99% identical), macaque NOS1 (99% identical), pig NOS1 (95% identical), dog NOS1 (94% identical), guinea pig NOS1 (94% identical), rat Nos1 (94% identical), mouse Nos1 (94% identical), tropical clawed frog nos1 (78% identical), zebrafish nos1 (74% identical). Paralogues in human: NOS3 (48% identical), NOS2 (43% identical), POR (14% identical), MTRR (12% identical), NDOR1 (11% identical).
Diseases named in the same sentence as NOS1 in open-access papers:
NOS1 is named in the same sentence as 334 diseases in open-access papers, as found by Europe PMC text mining. Sharing a sentence is not in itself a finding about the gene and the disease. The quoted sentences say what the papers report.
depression (63 papers, 2009 to 2026). "There were significant associations between 8 out of 20 NOS1 SNVs (rs693534, rs10507279, rs1004356, rs3782218, rs9658281, rs561712, rs522910, and rs2293050) and human liability to depression under exposure to financial and psychosocial stress factors." (PMID 32111088, 2020). "SNPs of NOS1 were already associated with several psychiatric disorders such as obsessive compulsive disorder, anxiety, and depression." (PMID 30813952, 2019). "Carriers of the minor NOS1 rs2682826 T allele had a higher probability of depression in a study of 763 southern Italians." (PMID 27555379, 2017). "In addition, NOS1 may be involved in psychological distress, suggesting that miR-146a polymorphism could have an effect on depression and anxiety." (PMID 31178808, 2019). "For example, polymorphisms on NO pathway genes, NOS1 (nNOS) and its adaptor protein NOS1AP are involved in PTSD severity, depression, anxiety, stress, and resilience, which strongly suggest its involvement in the pathophysiology of this disorder." (PMID 38202672, 2023). "The study (see Section 2.1.2 on “Depression and Bipolar Affective Disorder” regarding NOS1) also included the measurement of the subjects’ cognitive functions with the use of the MMSE (mini mental state examination) scale." (PMID 32111088, 2020). "Several studies have investigated the effects of NOS1 inhibition on behavioral tests of anxiety and depression." (PMID 22654729, 2011). "The chronic mild stress model of depression used in mice was shown to increase hippocampal NOS1 expression both acutely after 4 days and chronically after 21 or 56 days, with a coincident finding of decreased hippocampal neurogenesis in wild-type mice." (PMID 22654729, 2011). "Previously, our research group presented that different financial difficulties’ variables showed a specific interacting role with polymorphisms of NOS1 and 5-HTTLPR to affect depression, similarly as rs10462028 of CLOCK affected migraineID in the present study." (PMID 32038187, 2019). "Indeed, substantial evidence ranging from preclinical studies to human genetics and neuroimaging has linked NO and nNOS and/or its gene NOS1 to schizophrenia, bipolar disorder, major depressive disorder (MDD), attention-deficit/hyperactivity disorder (ADHD), and other mental illnesses." (PMID 41210888, 2026). "However, decreased NOS1 expression in the ACC was found in depression in depressive patients." (PMID 36051440, 2022). "Furthermore, an animal study suggests that the depression may be associated with increased activity of endothelial NOS (eNOS) and increased nNOS (neuronal NOS; NOS1) protein and mRNA expression in the hippocampus." (PMID 32281745, 2020). "This study shows the effects of chronic administration of agomelatine on expression and the methylation status of Sod1, Sod2, Gpx1, Gpx4, Cat, Nos1, and Nos2 in the brain stricture and blood in the chronic mild stress (CMS) animal model of depression." (PMID 32545212, 2020). "Numerous polymorphisms, occurring within this gene [especially g.117803515 C > T—NOS1 (rs1879417) and c.1823C > T—NOS2 (rs2297518)], play an essential role in the development mechanism of various diseases, including Fanconi anemia, depression, stroke, gastric, and urinary bladder cancer." (PMID 35732787, 2022).
diabetes (58 papers, 2005 to 2025). "According to the literature, early nephropathy occurring in diabetes is associated with increased intrarenal NO production, mainly mediated by neuronal nitric oxide synthase (NOS1, nNOS) and endothelial nitric oxide synthase (NOS3, eNOS)." (PMID 39061907, 2024). "Cat, Sod1, Sod2, Prkca, and Nos1 expression levels were decreased, while Ncf1, Xdh, and Cyba expression levels were increased in diabetes." (PMID 20979611, 2010). "We tested the hypothesis that in diabetes, tetrahydrobiopterin supplementation leads to the recoupling of nitric oxide synthase 1 (NOS1), preventing cardiac remodeling and the advance of diabetic nephropathy, two of the main complications of chronic diabetes." (PMID 36289741, 2022). "Downregulation of Nos1 in obesity and diabetes is largely attributed to insulin resistance." (PMID 33143653, 2020). "Our results show that neither diabetes nor homoarginine affected NOS1 or NOS2 gene expression in NOS3−/− mice." (PMID 33713581, 2021). "Between the two nitric oxide synthases tested in the present study, Nos1 (neuronal) expression was significantly decreased (p-value < 0.001) in diabetes, while Nos3 (endothelial) expression was not significant (p-value = 0.06)." (PMID 20979611, 2010).
Hypertension (58 papers, 2009 to 2025). The presence of chronic increased pressure in the systemic arterial system. "In particular, when analyzing both rat strains, a high correlation of Abcc1 and Nos1 expression was shown with the expression of the transcription factor gene Arnt associated with hypertension." (PMID 39594444, 2024). "The hypertension-associated genes Nos1 and Abcc1 are downregulated in the hypothalamus of both rat strains, and Cyp1b1 and Fos are ISIAH-specific DEGs associated with hypertension." (PMID 39594444, 2024). "Among the common DEGs that most significantly changed the transcription level during stress, two genes (Abcc1 and Nos1) associated with hypertension deserve the most attention." (PMID 39594444, 2024). "Associations of NOS1 with various diseases have been reported, such as schizophrenia, Parkinson’s disease, suicide, achalasia, multiple sclerosis, ischemic stroke, and hypertension." (PMID 29940959, 2018). "Disordered uric acid was supposed to influence changes in renin and NOS1 in the pathogenesis of hypertension, and it was mentioned as a modifying and causal factor for human primary hypertension." (PMID 26907309, 2016). "Associations were found between NOS1 variations with hypertension and changes in blood pressure." (PMID 37240727, 2023). "It has been observed that anti-VEGFR-2 antibody treatment in mice caused hypertension due to reduced NOS3 and NOS1 expression in the kidney." (PMID 39011232, 2024). "In contrast, a marked hypertension was evident in NOS1/NOS3 DKO mice, consistent with the idea that eNOS-derived NO regulates peripheral vascular resistance." (PMID 38255769, 2024). "As a result, NOS1 reduces myofilament Ca2+ sensitivity and promotes myocyte relaxation in hypertension." (PMID 35862303, 2022). "We propose that this difference may be related to the compensatory vasoregulatory mechanisms that are upregulated during chronic NO deficiency in the NOS1/3 DKO animals, and probably explain the milder hypertension in NOS KO compared to L-NAME-treated mice." (PMID 38255769, 2024). "Similarly, NOS1 expression and activity were increased in the LV myocytes of rats with Ang II-induced early hypertension." (PMID 33374571, 2020). "Certain changes in NOS1 appear to be related to high blood pressure or heart diseases such as CHD." (PMID 33374571, 2020). "The aim of the review is to study the role of SNVs of the NOS1, NOS2, and NOS3 genes in the comorbidity of arterial hypertension and tension-type headache." (PMID 33809023, 2021).
Stroke (53 papers, 2008 to 2025). Sudden impairment of blood flow to a part of the brain due to occlusion or rupture of an artery to the brain. "Amongst down-regulated proteins, Nos1 produces nitric oxide (NO) in the brain, a molecule associated with both neurotoxic and neuroprotective abilities in stroke." (PMID 32315348, 2020). "The g.117803515C > T (rs1879417) polymorphism of the NOS1 gene and stroke risk." (PMID 33808851, 2021). "NOS1, a family of NO synthases which synthesize NO from L-arginine is a pivotal mediator in neurotransmission, spatial learning and cognition and has been repeatedly implicated in the neurotoxicity associated with stroke and neurodegenerative disease." (PMID 28443016, 2017). "We hypothesize that single nucleotide polymorphisms (SNPs) in the SOD2, CAT, GPX4, NOS1 and NOS2 genes might be associated with altered susceptibility to oxidative stress and stroke development." (PMID 33808851, 2021). "In conclusion, our results showed that the genetics variants in the SOD2 (c.47T > C; rs4880), GPX4 (c.660T > A; rs713041), NOS1 (g.117803515C > T; rs1879417) and NOS2 (c.1823C > T; rs2297518 and c.-227G > C; rs10459953) genes may be associated with individual susceptibility to a stroke." (PMID 33808851, 2021). "The important biological targets for network pharmacological analysis of TM-CX and TM-JH related to stroke were PTGS2, ACE, APP, NOS1, and NOS2." (PMID 32328128, 2020). "In hippocampal tissues, mRNA expression studies at 1 h and 24 h, and strongly elevated (Egr1, Akt1, Kras, Src, Foxo, Srf, Vegfr2, Nos3, Nos1) and decreased (Nos2, Nfkb) gene expression (Mapk1 not activated) also support BPC 157 beneficial effect on brain lesions, given in reperfusion in stroke-rats." (PMID 34203464, 2021).
Anxiety (43 papers, 2009 to 2026). Intense feelings of nervousness, tension, or panic often arise in response to interpersonal stresses. "The conclusion of a genetic study conducted in humans proposes an association of the NOS1 genotype with anxiety." (PMID 38543047, 2024). "A recent study suggests interstingly, that the short allele of a functional promotor polymorphism of NOS1 (NOS1 ex1f-VNTR) may be associated with higher anxiety and altered fear conditioning in the human amygdala and hippocampus." (PMID 33713315, 2021). "These discoveries extend previous findings by linking NOS1 to alterations in the WM, representing a possible brain endophenotype of oxidative stress in anxiety and broadening its potential clinical service by revealing its value as a promising PD biomarker." (PMID 34733233, 2021). "NOS1 knockdown mice display a characteristic behavioral profile consisting of reduced anxiety and aggression and impaired cognitive metrics including learning and memory." (PMID 28443016, 2017). "PlcB4 and NOS1 were expressed at a high level in the medial septum and the hippocampus (two anxiety behavior-related regions), respectively, and inhibition of these genes in the regions with high levels of expression increased anxiolytic effects in a mouse model." (PMID 34763096, 2022). "Our study showed that chronic ketamine users carried more genotypic variations of rs6490121 and rs41279104 in the NOS1 gene than the control group and such variations were associated with more negative psychotic symptoms and fewer anxiety symptoms." (PMID 33424660, 2020).
schizophrenia (41 papers, 2009 to 2026). A major psychotic disorder characterized by abnormalities in the perception or expression of reality. "An apparent close connection between the ketamine and BPC 157 was noted in the genes’ expression analysis in brain tissue, using Nos1, Nos2, Nos3, Plcg1, Prkcg, Ptgs2, and Ptk2 all associated with schizophrenia presentation." (PMID 35884767, 2022). "This was done with the genes’ expression analysis in brain tissue, using Nos1, Nos2, Nos3, Plcg1, Prkcg, Ptgs2, and Ptk2, all associated with schizophrenia presentation." (PMID 35884767, 2022). "The promoter region of NOS1, affecting the prefrontal transmission of glutamate, has been repeatedly associated with schizophrenia." (PMID 32111088, 2020). "The blockade of the NMDA receptor and subsequent nitric oxide synthase 1 (NOS1) dysfunction were found to be closely correlated with schizophrenia including NOS1 gene polymorphisms." (PMID 33424660, 2020). "The genetic polymorphisms of NOS1 of the NMDAR-NO-cGMP pathway were also found to be closely related to schizophrenia." (PMID 33424660, 2020). "Two out of eight NOS1 SNVs, such as rs3782219 and rs3782221 (p = 0.0003 and p = 0.0014, respectively), appeared to be associated with schizophrenia." (PMID 32111088, 2020). "Recent studies have revealed that NOS1 variants are associated with disorders such as Alzheimer’s disease, schizophrenia, and Parkinson’s disease." (PMID 29940959, 2018). "NOS1 gene polymorphisms were combined with disturbance of cognitive functions both in patients with schizophrenia and in healthy persons." (PMID 26029110, 2015). "Recently, a whole genome association study reported an association between rs6490121 in intron 2 of NOS1 and schizophrenia." (PMID 21886582, 2011). "Several genetic association studies showed that single nucleotide polymorphisms (SNPs) in NOS1 were associated with schizophrenia." (PMID 21886582, 2011). "The neuronal nitric oxide synthase gene (NOS1) is located at 12q24, a susceptibility region for schizophrenia, and produces nitric oxide (NO)." (PMID 21886582, 2011). "This study underscores the role and regulation of nNOS within a specific subset of GABAergic interneurons, offering insights into the pathophysiological mechanisms of schizophrenia, given the association of Nrg1, Erbb4, Pi3k, and Nos1 genes with this mental disorder." (PMID 38396027, 2024). "Thus, the NOS1 gene was suggested as a candidate gene that increases the susceptibility to schizophrenia." (PMID 32111088, 2020). "Previous studies also provided evidence of the associations between NOS1 and schizophrenia risk." (PMID 30323833, 2018). "One of the papers by Chinese scientists where 11 polymorphisms of NOS1 gene are considered in 1705 patients has confirmed an association of polymorphism of rs3782206 and some haplotypes from 5′ flank region of the gene with schizophrenia." (PMID 26029110, 2015). "NOS1, which mediates the production of NO which plays a crucial role in schizophrenia and cognitive function, was found to be downregulated on treatment of neuroblastoma cells with WS." (PMID 40636521, 2025). "NOS1 coupling to the NMDA receptor is regulated by the NOS1 adapter protein (NOS1AP), whose polymorphisms are associated with schizophrenia and the severity of posttraumatic stress disorder." (PMID 36233204, 2022). "Alteration of the nitric oxide (NO) level via NMDAR blockade and subsequent nitric oxide synthase 1 (NOS1) dysfunction was found to be closely correlated with schizophrenia." (PMID 33424660, 2020). "The interaction between HIF-2 signalling and NOS1 signalling, another candidate pathway with pharmagenic enrichment in schizophrenia, is supported by previous evidence of redox dysfunction in the disorder." (PMID 31964963, 2020). "Blockade of NOS1 was found to enhance PCP-induced schizophrenia-like symptoms and to increase c-fos gene expression in the cortical region." (PMID 33424660, 2020).